PLA2G4F (phospholipase A2 group IVF)
Description:
Has calcium-dependent phospholipase and lysophospholipase activities with a potential role in membrane lipid remodeling and biosynthesis of lipid mediators. Preferentially hydrolyzes the ester bond of the fatty acyl group attached at sn-2 position of phospholipids (phospholipase A2 activity). Selectively hydrolyzes sn-2 arachidonoyl group from membrane phospholipids, providing the precursor for eicosanoid biosynthesis. In myocardial mitochondria, plays a major role in arachidonate release that is metabolically channeled to the formation of cardioprotective eicosanoids, epoxyeicosatrienoates (EETs).
Synonyms: PLA2G4F/Z; PLA2G4FZ
Tractability: Antibody: UniProt places it where antibodies can reach, with high confidence; its Gene Ontology location is reachable by antibodies, with medium confidence.
Gene: Protein-coding gene on chromosome 15 (42,139,034 to 42,156,659, reverse strand). Ensembl gene ENSG00000168907.
Subcellular location: Cytoplasm, cytosol; Cell membrane; Mitochondrion
Subcellular location (Human Protein Atlas): Vesicles; Nucleoplasm
Pathways (Reactome):
Metabolism: Acyl chain remodelling of PC; Acyl chain remodelling of PE; Acyl chain remodelling of PG; Acyl chain remodelling of PI; Acyl chain remodelling of PS; Hydrolysis of LPC
Gene Ontology:
Molecular function: phospholipase A2 activity; calcium ion binding; calcium-dependent phospholipid binding; phospholipase A1 activity; phosphatidylcholine lysophospholipase activity; phospholipase activity
Biological process: glycerophospholipid catabolic process; phosphatidylglycerol acyl-chain remodeling; glycerophospholipid metabolic process; phospholipid catabolic process
Cellular component: mitochondrion; cytosol; plasma membrane; ruffle membrane; vesicle; cytoplasm
Genetic constraint (gnomAD): Loss-of-function variants: 104 observed, 99.07 expected, observed/expected ratio (o/e) 1.05, 90% interval 0.89 to 1.24. The upper end of that interval is the gene's LOEUF score, 1.24, which puts it in group 5 of 6, group 1 being the genes least tolerant of losing a copy. Missense variants: 1,129 observed, 1,065.4 expected, observed/expected ratio (o/e) 1.06, 90% interval 1.01 to 1.11. Synonymous variants: 457 observed, 433.63 expected, observed/expected ratio (o/e) 1.05, 90% interval 0.98 to 1.14.
Homologues: Orthologues: chimpanzee PLA2G4F (98% identical), macaque PLA2G4F (93% identical), pig PLA2G4F (84% identical), dog PLA2G4F (83% identical), guinea pig PLA2G4F (77% identical), mouse Pla2g4f (74% identical), rat Pla2g4f (73% identical), rabbit PLA2G4F (73% identical), tropical clawed frog pla2g4f (53% identical). Paralogues in human: PLA2G4D (38% identical), PLA2G4E (38% identical), PLA2G4B (37% identical), PLA2G4A (27% identical), PLA2G4C (18% identical).
Diseases named in the same sentence as PLA2G4F in open-access papers:
PLA2G4F is named in the same sentence as 11 diseases in open-access papers, as found by Europe PMC text mining. Sharing a sentence is not in itself a finding about the gene and the disease. The quoted sentences say what the papers report.
colitis (2 papers, 2012 to 2024). Inflammation of the colon. "Specifically, differential expressed genes (DEGs) related to colitis such as Mmp10, Tnfaip3, Lcn2, Serpine1, and Pla2g4f were upregulated in the colon tissue of colitis mice in DVF group." (PMID 38172943, 2024). "Among the remaining 10 genes, we identified Pla2g4f and Duox2 as the most likely colitis gene candidates, because GPX metabolizes PLA2G4F and DUOX2 products." (PMID 22970191, 2012). "Therefore, we have selected Duox2 and Pla2g4f as prime candidates for further analysis of their roles in murine colitis models and human IBD." (PMID 22970191, 2012). "We then explain the rationale for why we chose Pla2g4f and Duox2 as the top colitis gene candidates rather than eight other genes that included Bub1b, Plcb2, Casc5, Chac1, Oip5, Pla2g4e, Trp53bp1 and Slc28a2." (PMID 22970191, 2012).
prostate carcinoma (1 paper, 2022). A carcinoma that arises from epithelial cells of the prostate gland. "Patient-derived prostate cancer xenografts grown as organoids have increased uptake of ArA in models with increased MYC activity and PLA2G4F expression." (PMID 36181613, 2022). "Here, we report that in prostate cancer cells, differential binding of AR and HOXB13 on account of varying MYC levels centers on genes regulated by KMT2A/MLL1, which in turn is inversely proportional to the expression of PLA2G4F in cohorts of advanced, but not localized, PCa." (PMID 36181613, 2022).
schizophrenia (1 paper, 2024). A major psychotic disorder characterized by abnormalities in the perception or expression of reality. "This study indicated that in the discovery stage, an increased copy number of PLA2G6 and the deletion of PLA2G3, PLA2G4A, PLA2G4F and PLA2G12F was associated with increased risk of schizophrenia." (PMID 38816399, 2024).
synovitis (1 paper, 2018). Inflammation of a synovial membrane. "Genes such as NRAS, SPHK2, FOS, CXCR4, PLD1, GNAI2, and PLA2G4F were strongly implicated in synovitis of OA." (PMID 29968759, 2018).
cancer (5 papers, 2018 to 2023). A tumor composed of atypical neoplastic, often pleomorphic cells that invade other tissues. "The arachidonic acid metabolic enzyme PLA2G4F encodes a Group IV cytosolic phospholipase A2 with high specificity for arachidonic acid that is preferentially metabolized by cancer cells." (PMID 38110715, 2023). "The central premise of our finding relies on the observation that MYC is rewired from opposing PLA2G4F expression in early cancer to being positively associated with it in progressively advanced disease." (PMID 36181613, 2022). "Genes such as NRAS, SPHK2, FOS, CXCR4, PLD1, GNAI2, and PLA2G4F, and their related biological process terms and pathways, such as apoptosis, MAPK signalling pathway, and cancer signalling pathways, may represent potential targets for OA treatment and diagnosis." (PMID 29968759, 2018).
infection (3 papers, 2022 to 2025). The state of being infected such as from the introduction of a foreign agent such as serum, vaccine, antigenic substance or organism. "Several genes were significantly upregulated (Pla2g4a, Pla2g4c, Pla2g7, Ptgs1, Ptgs2, Pla1, Tbxas1) or downregulated (Alox5, Pla2g2d, Pla2g1b, Pla2g4b, Pla2g4f) during infection." (PMID 35812400, 2022). "In addition, genes related to glycerolipid metabolism (Plpp2), glycolysis metabolism (Pfkp), adipocyte differentiation (Rapgef4), nucleotide metabolism (Entpd3), serine catabolism (Shmt1), retinol metabolism (Akr1b10), and lipid-grading metabolism (Pla2g4f) were upregulated after EgPSC infection." (PMID 36713407, 2022). "In the intestine, coinfection resulted in the distinct upregulation of multiple inflammatory and stress-related gene signatures, including FOLR2 and PLA2G4F, which were not significantly upregulated in the single-infection cohorts." (PMID 41268552, 2025).
tumor (3 papers, 2022 to 2025). "This study highlights the metabolic heterogeneity in TNBC and identifies PLA2G4F as a pro-tumor factor, suggesting it as a potential novel therapeutic target." (PMID 40212962, 2025). "Compared to adjacent normal tissues, tumor tissues exhibited significantly reduced expression of PTGIS, DGKB, HSD17B13, INMT, and ACACB, while PLA2G10, GRHL1, LIPG, and PLA2G4F were markedly upregulated." (PMID 40426878, 2025).
PLA2G4F also shares sentences with these, for which no sentence is quoted: melanoma (2 papers); colon cancer (1); gastric cancer (1); triple-negative breast carcinoma (1).